RNU6-1074P (RNA, U6 small nuclear 1074, pseudogene)
Gene: Small nuclear RNA gene on chromosome 4 (139,256,657 to 139,256,760, reverse strand). Ensembl gene ENSG00000206722.
Homologues: Orthologues: chimpanzee U6 (100% identical), macaque U6 (88% identical). Paralogues in human: RNU6-21P (88% identical), RNU6-25P (88% identical), RNU6-1 (87% identical), RNU6-15P (87% identical), RNU6-19P (87% identical), RNU6-2 (87% identical), RNU6-20P (87% identical), RNU6-29P (87% identical), RNU6-356P (87% identical), RNU6-35P (87% identical), RNU6-3P (87% identical), RNU6-492P (87% identical), and 1283 more.